TRIM8 (tripartite motif containing 8)
Diseases named in the same sentence as TRIM8 in open-access papers (continued):
Sharing a sentence is not in itself a finding about the gene and the disease.
cancer (continued). "The TRIM8 mRNA expression in LV-TRIM8 cancers was about 6.6-fold higher than that in LV-Ctrl cancers (p < 0.01)." (PMID 33858426, 2021). "TRIM8 overexpression downregulated the protein expressions of Wnt5a, β-Catenin, c-Myc and Cyclin D1, and upregulated the protein expression of active Caspase-3 in LV-TRIM8 cancers." (PMID 33858426, 2021). "In this study, we sought to investigate the effects of the TRIM8 protein on ΔNp63 isoforms and in particular, on the oncogenic ΔNp63α, the main p63 isoform involved in cancer development." (PMID 31781486, 2019). "Nevertheless, TRIM8 is involved in other cellular functions tightly related to cancer, such as inflammation and innate immunity." (PMID 29182544, 2017). "To treat cancer cells with TRIM8 or RING-TRIM8, we devised a strategy based on the use of recombinant replication-incompetent adenoviruses." (PMID 28327152, 2017). "TRIM8 plays divergent roles in many biological processes, including important functions in inflammation and cancer through regulating various signalling pathways." (PMID 29182544, 2017). "Recently, we showed that TRIM8 protein has a prominent role in regulating cancer cell growth in vivo in ccRCC." (PMID 28327152, 2017). "Our data corroborate mounting evidence showing a downregulation of TRIM8 in different cancers and its role in controlling cell growth." (PMID 26077989, 2015). "Also, TRIM8 stabilizes the X-linked inhibitor of apoptosis (XIAP), a molecule modulating cell death and autophagy, thereby promoting the survival of cancer cells." (PMID 39224802, 2024). "Therefore, TRIM8 has been reported to play important but divergent roles in various types of cancer." (PMID 38879600, 2024). "Moreover, the cancer-promoting effects of TRIM8 in HCC were abolished by the HNF1α-K197R mutant in vitro and in vivo." (PMID 38879600, 2024). "Fusing guide peptides to an E3 ubiquitin ligase domain, we demonstrate degradation of endogenous β-catenin, 4E-BP2, and TRIM8, and highlight the nanomolar binding affinity, low off-targeting propensity, and function-altering capability of our best-performing degraders in cancer cells." (PMID 37875551, 2023). "Moreover, to further investigate the expression of TRIM8 in human cancers, we performed a detailed analysis of RNA-Seq data from TCGA." (PMID 35368651, 2022). "TRIM8 regulates the clone formation and migration ability of cancer cells by NF-κB pathway." (PMID 36353542, 2022). "Therefore, TRIM8 avoids cell death during genotoxic stress and radiation therapy, suggesting that TRIM8′s highly oncogenic potential can allow survival assistance to cancer cells." (PMID 35565438, 2022). "The TRIM8 protein expression also increased in LV-TRIM8 cancers." (PMID 33858426, 2021). "Up to now, the function and mechanism of TRIM8 in plenty of cancers, including LUSC, is still unknown." (PMID 33858426, 2021). "In the development of cancer, TRIM8 seems to have a dual role." (PMID 33118318, 2020). "A prominent role for TRIM8 in regulating cancer cell growth was shown in vivo in ccRCC." (PMID 29182544, 2017). "Here, to elucidate the molecular mechanisms leading to this gene expression alteration, we tested the possible correlation with the expression levels of two miRNA, miR-17-5p and miR-106b-5p, since they are up-regulated in chemo/radio-resistant cancers and the miR-17-92 cluster targets TRIM8 mRNA." (PMID 28327152, 2017). "Previous studies have reported that TRIM8 negatively regulates PIAS3 in cancer cell lines." (PMID 28100038, 2017).
cancer (continued). "The further study will help to understand the role of TRIM8 in inflammation and cancer." (PMID 23152791, 2012). "The role of another TRIM family protein, TRIM8, as a ‘double-edged sword’ in promoting or suppressing cancers, was reviewed extensively, illustrating the differential expression of TRIM8 and its respective mode of intervention in regulating cancer-related pathways." (PMID 39451518, 2024). "In addition, rescue experiments showed that VDAC2 could reduce the cancer‐promoting effect induced by TRIM8." (PMID 38881325, 2024). "Similarly, TRIM8 exerts more than one role in quite diverse pathways, as in embryonic development and differentiation, in innate immune response and in a variety of human cancers." (PMID 28327152, 2017). "Recently, tri‐partite motif‐containing protein 8 (TRIM8) has been shown to interact with PIAS3, either by causing its degradation through the ubiquitin‐proteasome pathway or through its exclusion from the nucleus, resulting in enhanced STAT3‐dependent signaling in a subset of cancer cell lines." (PMID 28100038, 2017). "TRIM8 interacts with and negatively regulates PIAS3, a protein inhibitor of IL-6-dependent activation of STAT3, a signaling pathway important for cancer development and progression." (PMID 26077989, 2015). "In addition, TRIM8 mediates stable XIAP, and prevents the activation of caspase-3, thereby inhibiting cell apoptosis, and promoting cancer." (PMID 36353542, 2022). "TRIM8 was found differentially expressed in melanoma together with other TRIMs (TRIM2, TRIM7, TRIM18, TRIM19, TRIM27 and TRIM29), playing an important role in the development of this cancer." (PMID 33807506, 2021). "The TRIM8/STAT3 positive feedback loop in GBM provides new insight into the regulation of STAT3 and offers new opportunities for the development of treatments that impair stemness in GSC and potentially in other cancers that show TRIM8 overexpression." (PMID 29182544, 2017).
infection (4 papers, 2017 to 2025). The state of being infected such as from the introduction of a foreign agent such as serum, vaccine, antigenic substance or organism. "We observed an upregulation of TRIM8 following PEDV infection and identified differentially expressed genes associated with TRIM8 expression in response to this infection." (PMID 39819815, 2025). "The results showed that the expression level of the TRIM8 gene was significantly upregulated at 12, 24, and 48 h of infection, with the highest level observed at 24 h post-infection." (PMID 39819815, 2025). "Next, we selected three TRIM genes, namely TRIM8, 14, and 17, to study changes in the expression of the corresponding proteins in cell line U937 after infection with P. aeruginosa, C. pneumoniae, and C. trachomatis." (PMID 37686095, 2023). "TRIM8, 14, and 68 were increased in U937 cells in response to all the pathogens examined, as well as in mouse lungs upon both infections, and in A549 after C. pneumoniae infection." (PMID 37686095, 2023). "Additionally, the western blot assay confirmed the changes in TRIM8 expression at different infection time points following infection." (PMID 39819815, 2025). "Next, we established HeLa stable cells expressing TRIM8, TRIM25, TRIM26, TRIM32, and TRIM33 to evaluate their effects on VEEV-TC83-GFP infection." (PMID 39527628, 2024).
neurological disorder (3 papers, 2022 to 2025). "Two patients with TRIM8 variants closer to the N-terminal had neurological diseases without renal damage." (PMID 39416667, 2024). "Five patients with TRIM8 variants closer to the C-terminal had no severe neurological diseases." (PMID 39416667, 2024).
bacterial infections (1 paper, 2023). "Western blot analysis showed changes in TRIM8 and TRIM14 protein expression, confirming the involvement of the proteins in the immune response to the studied bacterial infections." (PMID 37686095, 2023).
cardiovascular diseases (1 paper, 2021). "Recent studies show that TRIM8 is involved in several disorders, including Ischemia/Reperfusion (I/R) injury and cardiovascular diseases." (PMID 33807506, 2021).
metabolic disorders (1 paper, 2025). "Overexpression of TRIM8 results in a significant increase in TAK1 phosphorylation, which in turn causes IR and metabolic disorders in HFD-fed NASH mice." (PMID 40292292, 2025). "This implies that inhibition of the ubiquitination pathway of TRIM8 is promising for the treatment of NASH-related metabolic disorders." (PMID 40292292, 2025).
renal system diseases (1 paper, 2023). "Eight reports have described neurological and renal system diseases associated with TRIM8 variants, and all of them were de novo truncating variants in the last exon of TRIM8." (PMID 37061734, 2023).
TRIM8 also shares sentences with these, for which no sentence is quoted: focal segmental glomerulosclerosis (3 papers); autoimmune (2); benign oncocytoma (2); Chronic lymphocytic leukemia (2); laryngeal squamous cell carcinoma (2); acute lung injury (1); acute lymphoblastic leukemia (1); allergic disease (1); atrial fibrillation (1); autoimmune glomerulonephritis (1); bone sarcoma (1); breast invasive carcinoma (1); colon adenocarcinoma (1); corneal ulceration (1); endothelial dysfunction (1); esophageal cancer (1); heart diseases (1); heart failure (1); liver cancer (1); liver inflammation (1); myocardial infarction (1); neuroblastoma (1); neurodevelopmental disorder (1); non-alcoholic steatohepatitis (1); prostate adenocarcinoma (1); prostate carcinoma (1); Proteinuria (1); rectum adenocarcinoma (1); renal disorders (1); sarcoma (1).
A further 4 diseases each share a sentence with TRIM8 in 1 paper.